SLFN11 (schlafen family member 11)
Diseases named in the same sentence as SLFN11 in open-access papers (continued):
Sharing a sentence is not in itself a finding about the gene and the disease.
cancer (continued). "As these drugs lead to replication fork stalling and cell cycle checkpoint activation, replication stress appears to be the common mechanism by which SLFN11 sensitizes cancer cells to DDAs22." (PMID 36115853, 2022). "The human Schlafen family member SLFN11 came into focus due to its ability to promote cancer cell death in response to DNA-damaging agents." (PMID 35037067, 2022). "Based on promising findings from preclinical studies, the predictive role of SLFN11 is being assessed across different cancer types in a clinical setting." (PMID 35625957, 2022). "Tumor samples showed a greater than fivefold SLFN11 expression range compared to healthy tissues, with several cancer samples having a higher or lower SLFN11 expression than the interquartile range for its expression in normal tissues (p-value < 0.05)." (PMID 35625957, 2022). "A similarly complicated role can be assumed for SLFN11, which was found to exhibit a broad range of expression in a The Cancer Genome Atlas (TCGA) pan-cancer dataset, and the NCI-60 cancer cell line panel." (PMID 36382088, 2022). "SLFN11 appears to enhance cancer cells’ sensitivity to a wide range of anticancer drugs, including platinum derivatives, DNA synthesis inhibitors such as gemcitabine, and topoisomerase inhibitors such as irinotecan." (PMID 35715750, 2022). "Taken together, these findings are suggestive of a close, hitherto scarcely investigated link between SLFN11 and cancer immunity in HGSOC." (PMID 34549724, 2021). "For instance, the selection of patients according to the expression of Schlafen 11 (SLFN11) has recently been reported to be correlated with improved response in several human cancer types." (PMID 34572827, 2021). "In our analyses, we demonstrate that SLFN11 in cancer and immune cells is independently a predictor of response to CT in HGSOC." (PMID 34549724, 2021). "Based on the findings in cancer cells-based models, the clinical exploitation of SLFN11 expression as a treatment biomarker is being actively explored." (PMID 34572827, 2021). "We analyzed the expression of SLFN11 by mining cell line databases for different stages of normal B-cells and various types of B-cell-derived cancer cell lines." (PMID 33513156, 2021). "SLFN11 has been shown to predict response to DDA in different cancer models, but to our knowledge, we describe here for the first time that SLFN11 has more predictive power when its expression in the stromal noncancer compartment is taken into account." (PMID 34549724, 2021). "As SLFN11 is a promising target to sensitize tumor cells to cytotoxic chemotherapy, regulatory factors of SLFN11 expression are also favorable targets for cancer treatment." (PMID 33513156, 2021). "SLFN11 has recently been reported to execute cancer cells harboring replicative stress induced by DNA damaging agents." (PMID 33513156, 2021). "The correlations with SLFN11 were in general weaker than the ones observed among markers of inhibition, activation, and exhaustion, most likely due to the complex regulation and expression of SLFN11 in both cancer cells and immune cells." (PMID 34549724, 2021). "By focusing on DDA, we provide novel sensitisation strategies for SLFN11 low cancers, with evidence suggesting DDA combinations with WEE1i, ATRi or CHKi can overcome resistance arising from low or absent SLFN11." (PMID 33339894, 2021). "SLFN11 expression in human cancers is positively correlated with sensitivity to genotoxic agents, including topoisomerase inhibitors." (PMID 33925464, 2021). "Our results are consistent with and lend additional support to the notion that the expression levels of ABCB1 and SLFN11 are potential biomarkers for cancer cell line sensitivity to multiple drugs." (PMID 33858332, 2021). "Correspondingly, expression of SLFN11 in resistant cancer cell lines induced by class I HDAC inhibitors restored their sensitivity." (PMID 33925464, 2021).
cancer (continued). "Correlation analysis reveals that SLFN11 expression is significantly correlated with the activity of AraC, indicating the potential utility of SLFN11 expression as predictor of drug activity for AraC in B-cell-derived cancers." (PMID 33513156, 2021). "Taken together, these results point at a complex interplay between SLFN11 in cancer cells and the immune system in cancer, which fosters further investigation." (PMID 34549724, 2021). "Recently, it has been reported that SLFN11 in cancer cells activates an innate immune stress response following DDA treatment and replication stress." (PMID 34549724, 2021). "Recent functional studies on cancer cell lines have identified SLFN11 as the strongest predictor of sensitivity to DNA-damaging agents (DDAs), including platinum-based chemotherapy." (PMID 35008168, 2021). "In 2012, we discovered that SLFN11 is a dominant predictor of response to replication damaging agents widely used in cancer chemotherapy including TOP inhibitors, nucleoside analogues, platinum-based, and alkylating agents." (PMID 34572827, 2021). "In summary, the current study shows that SLFN11 in both cancer cells and a multitude of immune cells and potentially other (to-be-defined) cell types are associated with a better prognosis of HGSOC patients treated with platinum-containing regimens." (PMID 34549724, 2021). "Large independent analyses on cancer cell lines followed by functional studies have identified Schlafen 11 (SLFN11), a putative helicase, as the strongest predictor of sensitivity to DNA-damaging agents (DDAs), including platinum." (PMID 34549724, 2021). "An in-depth understanding of several aspects of its role as a biomarker in cancer is missing, as is a comprehensive analysis of the clinical significance of SLFN11 as a predictive biomarker to DDA and/or DNA damage-response inhibitor (DDRi) therapies." (PMID 33339894, 2021). "For instance, cancer cells expressing high SLFN11 but with high expression of the drug efflux genes ABCB1 (encoding P-glycoprotein) are unlikely to respond to doxorubicin." (PMID 34572827, 2021). "Taken together, these results demonstrate that DDA treatment triggers immune-related gene expression and an activation of an immune response in SLFN11-proficient cancer cells." (PMID 34549724, 2021). "Studies performed at different cancer research centers have established the feasibility of immunohistochemistry (IHC)-based detection of SLFN11 in malignant and adjacent normal tissues." (PMID 34572827, 2021). "Yet, exploitation of SLFN11 promoter methylation needs to be interpreted with caution as a large number of cancer cells also suppress SLFN11 expression by histone acetylation, which escapes from promoter methylation evaluations." (PMID 34572827, 2021). "Consistent with previous reports based on cancer cell database correlations, SLFN11-proficient cells were highly sensitive to carboplatin and nedaplatin compared to SLFN11-deficient cells." (PMID 33218331, 2020). "We believe that examination of SLFN11 expression is useful in ensuring the optimal selection of anti-cancer treatment." (PMID 33218331, 2020). "In this setting cancer cell lines with high SLFN11 expression had better therapeutic sensitivity to nedaplatin than those with low SLFN11 expression." (PMID 33218331, 2020). "Functional enrichment analysis further indicated that cancer and cell death and survival were ranked as the top 2 and 3 molecular networks, respectively, in the cluster of SLFN11-enriched proteins." (PMID 32292519, 2020). "Our PC3 cell data indicates that CD47 regulation of SLFN11 and responses to stress is more restricted in this cancer cell line." (PMID 31632920, 2019). "Correspondingly, expression of SLFN11 in some resistant cancer cell lines can be induced by class I HDAC inhibitors and restores their sensitivity, whereas knockdown of SLFN11 confers resistance." (PMID 31632920, 2019).
cancer (continued). "SLFN11 expression was consistently higher and lower in certain cancer types (e.g. kidney and large intestine/colon, respectively)." (PMID 31682620, 2019). "Previous studies have identified SLFN11 expression as a major determinant of cancer cell sensitivity to DNA-damaging chemotherapeutic agents and patient outcomes for several cancers." (PMID 31632920, 2019). "A positive correlation between CD47 and SLFN11 was also found for the cell lines in the Cancer Cell Line Encyclopedia (Spearman's correlation 0.193, p = 1.6 × 10−9, q = 2.6 × 10−8)." (PMID 31632920, 2019). "One of these, the class I HDAC inhibitor entinostat (HDAC1>HDAC3), was previously shown to restore SLFN11 expression and sensitivity to DNA damage in resistant cancer cell lines." (PMID 31632920, 2019). "Others also found that SLFN11 knockdown conferred resistance to an alkylating agent and PARP inhibitors; these drugs induced downregulation of SLFN11 levels in cancer cells, potentially explaining the link between low SLFN11 levels and chemoresistance." (PMID 31682620, 2019). "The sensitivity of cancer cells to chemotherapeutic drugs can be restored by inhibiting SLFN11 methylation in vivo." (PMID 31514451, 2019). "An initial survey of TCGA cancer datasets with sufficient RNAseq data indicated that the positive correlation between CD47 and SLFN11 mRNA expression observed in Jurkat T cells extends to a subset of human cancers." (PMID 31632920, 2019). "High levels of SLFN11 sensitize cancer cells to DNA damaging agents by suppressing checkpoint maintenance and homologous recombination repair." (PMID 31393969, 2019). "Schlafen 11 (SLFN11) is widely expressed in a variety of cancer cells, and its expression levels are related to the sensitivity of cells to chemotherapeutic drugs, especially DNA-damaging agents (DDAs)." (PMID 31514451, 2019). "CD47 mRNA expression was also negatively correlated with SLFN11 promoter methylation in some cancers." (PMID 31632920, 2019). "Further studies will be required to define the relative importance of these two mechanisms in the cross talk between CD47 and SLFN11 in each cancer type." (PMID 31632920, 2019). "It is worth mentioning that SLFN11 is inactivated in about 50% of cancer cell lines and most tumors, and cells with lower expression of SLFN11 are highly sensitive to chemotherapeutic drugs." (PMID 31514451, 2019). "In contrast, EHF is negatively correlated with SLFN11 expression in other cancers from NCI60 and CCLE data sets." (PMID 28212573, 2017). "One emerging biomarker for PARP inhibitors and chemotherapy in several cancers is Schlafen 11 (SLFN11)." (PMID 28212573, 2017). "All normal tissues analyzed in our cohort (n = 64), counterparts of the NCI60 cancer types, were found to be unmethylated at the SLFN11 CpG island." (PMID 26625211, 2016). "Overall, these results identify SLFN11 epigenetic inactivation as a predictor of resistance to platinum drugs in human cancer." (PMID 26625211, 2016). "Our data mining of the NCI-60 readily picked talazoparib, the most potent PARP trapping inhibitor as showing a highly significant correlation between cancer cell killing and SLFN11 transcript levels." (PMID 27708213, 2016). "In this study, we demonstrate the importance of SLFN11 expression as a determinant of response to talazoparib in cancer cell lines and in xenograft models, and extend these findings to olaparib and to the combination of talazoparib with temozolomide." (PMID 27708213, 2016). "Independently, SLFN11 was identified as a predictive genomic biomarker for Top1 inhibitors in the larger database of the Cancer Cell Line Encyclopedia (CCLE)." (PMID 27708213, 2016). "Our study reveals that SLFN11 inactivation, which is common (~45%) in cancer cells, is a novel and dominant resistance determinant to PARPIs." (PMID 27708213, 2016). "SLFN11 is epigenetically silenced and confers chemoresistance in half of all cancers." (PMID 41514018, 2026).
cancer (continued). "We believe that in ccRCC, this immunomodulatory effect of SLFN11 dominates the cancer-promoting mechanism and may mask the impact of its function in DNA damage response on current mainstream treatment options." (PMID 40766331, 2025). "Furthermore, we discuss the potential of SLFN11 expression status in overcoming resistance to DNA-damaging drugs, optimizing treatment strategies, and advancing precision cancer therapy." (PMID 40766331, 2025). "Finally, we discuss the potential of SLFN11 in overcoming drug resistance, optimizing treatment strategies, and advancing precision cancer therapy." (PMID 40766331, 2025). "Therefore, dynamic detection of SLFN11 expression is particularly important for the precise treatment of cancer patients." (PMID 40766331, 2025). "Our studies aiming to expand the potential clinical reach of FEN1 inhibitors beyond the HRD setting, identified EWS cells and more generally, SLFN11 expressing cancer cells, as potentially sensitive populations, which is consistent with the role of Schlafen-11 in response to RS-inducing DDRi/DDAs." (PMID 41359388, 2025). "We speculate that monotherapy activity is driven by inhibition of DNA replication and repair, providing a foundation for targeting HRD and DDR defective cancer cells with an altered RS response e.g. SLFN11 high." (PMID 41359388, 2025). "Summary of the roles, mechanisms and the clinical significance of SLFN11 in different cancer types." (PMID 40766331, 2025). "Additionally, a new family of proteins named Schlafen (SLFN) was acknowledged for being crucial for hPARP activity, especially SLFN-11, and was found to be a predictive biomarker for hPARP inhibitor-sensitive cancer types." (PMID 40649247, 2025). "More importantly, SLFN11 is closely associated with the shaping of the immunosuppressive tumor microenvironment (TME) in ccRCC, which constitutes another key mechanism for its cancer promotion." (PMID 40766331, 2025). "Studies that evaluated SLFN11 as a prognostic or predictive biomarker in cancer patients." (PMID 40766331, 2025). "Over the past decade, SLFN11 has been extensively studied for its relevance to cancer therapy." (PMID 40766331, 2025). "Importantly, these fluctuations can be therapeutically targeted: deacetylase inhibitors restore SLFN11 expression, reactivating its tumor-suppressive functions and sensitizing resistant cancer cells to DNA-damaging treatments." (PMID 41303540, 2025). "Lastly, SLFN11 has been proven to respond to DNA damage in studies of various cancer cells." (PMID 40563861, 2025). "Deficiency of mismatch repair proteins was detected in 65% (20/31) of SLFN11‐positive carcinomas." (PMID 40105034, 2025). "SLFN12, like SLFN11, increases the medication sensitivity of malignant tumors." (PMID 38832156, 2024). "This upregulation of SLFN11 may contribute to the sensitivity of cancer cells to platinum-based drugs and their subsequent therapeutic effects." (PMID 38790938, 2024). "SLFN11 has been shown to sensitize cancer cells to chemotherapy and radiation through five different mechanisms, which may allow for SLFN11 to act as a biomarker for predicting a patient’s response to DNA-damaging agents." (PMID 39594803, 2024). "As the accumulation of single-strand DNA (ssDNA) gaps behind replication forks is key for the lethality effect of PARPis, we investigated the combined effects of SLFN11 expression and BRCA deficiency on PARPi sensitivity and ssDNA gap formation in human cancer cells." (PMID 38961202, 2024). "Because SLFN11 (Schlafen 11) expression in cancer cells has been reported to determine their sensitivity to a wide range of DNA-damaging anticancer drugs, including topoisomerase, PARP inhibitors, and platinum-based drugs, we examined SLFN11 expression in theACC cell lines and surgical samples." (PMID 39162009, 2024).
cancer (continued). "Work from several groups has demonstrated the reliance on the ATR/Chk1 pathway in cancers that express little to no SLFN11, making these cancers more susceptible to ATR inhibition." (PMID 38791884, 2024). "The transcripts were selected to inform about diverse resistance mechanisms (AR-V7 expression, neuroendocrine transdifferentiation), druggable targets and predictive markers (PSMA, DLL3, SLFN11), and cancer-related processes such as epithelial mesenchymal transition (VIM, KRT)." (PMID 39550585, 2024). "Furthermore, the ATPase function of SLFN11 is essential for eliminating cancer cells with replicating DNA damage and open chromatin, resulting in fatal replication pause and the induction of stress response genes within the FOS-JUN pathway." (PMID 39558948, 2024). "In the context of cancer, SLFN11 helps sensitize cancer cells to DNA-damaging agents like topoisomerase I and II inhibitors (such as irinotecan and etoposide, respectively), DNA synthesis inhibitors (e.g., gemcitabine), and DNA cross-linkers and alkylating agents (e.g., cisplatin)." (PMID 38790938, 2024). "For instance, the re-expression of SLFN11 in cancer cells that have silenced its expression through various mechanisms of transcriptional silencing could increase sensitivity to a variety of DDAs." (PMID 38791884, 2024). "SLFN11 is a crucial gene in the SLFN family that makes cancers more sensitive to chemotherapeutics." (PMID 38832156, 2024). "The use of a CRISPR-dCas9 UNISAM and KRAB system could increase or decrease SLFN11 expression significantly (up to fivefold), stably and specifically in BT-549 and T47D cancer cell lines." (PMID 38001424, 2023). "Furthermore, the camptothecin-induced upregulation of multiple AP-1 transcription factors is significantly correlated with the basal SLFN11 expression levels for 55 cell lines (NCI-60 panel) representing multiple cancer types." (PMID 37599787, 2023). "Importantly, human clinical tumors often lose expression of SLFN11 during carcinogenesis and following chemotherapeutic treatments because of epigenetic silencing, and common human cancer cell lines often lack its expression." (PMID 37833372, 2023). "All modified cell lines were screened by CWB and Q-RT-PCR to identify the most efficient single gRNA that could successfully modulate SLFN11 expression levels in the selected cancer cells." (PMID 38001424, 2023). "Further investigation is needed to determine whether SLFN11 has heterogeneous effects on the response to Topotecan in patients with different cancer types." (PMID 38081913, 2023). "Hypothesizing that in cancers which are resistant to chemotherapy, upregulation of SLFN11 can restore their chemosensitivity." (PMID 38001424, 2023). "Next to a predictive biomarker SLFN11 could be a therapeutic target for sensitizing cancer cell to chemo, radio, or immunotherapy." (PMID 38001424, 2023). "Also, the potential of SLFN11 as a prognostic biomarker has been confirmed in hepatocellular, gastric, esophageal, and bladder cancer, in the majority of which SLFN11 expression was examined by immunohistochemistry." (PMID 37894765, 2023). "Thus, several strategies aimed at increasing SLFN11 are explored to restore chemosensitivity of refractory cancers." (PMID 38001424, 2023). "However, the SLFN11 gene is generally silenced in cancer cells, making these cancer cells more capable of DNA repair and conferring resistance to PARPi." (PMID 36091750, 2022). "Recently, Schlafen family member 11 (SLFN11) has been reported to increase the sensitivity of cancer cells to DNA-damaging agents, including platinum derivatives; thus, SLFN11 may be a predictive biomarker for platinum-based chemoradiotherapy (CRT)." (PMID 36741698, 2022). "SLFN11 has been described as a promising biomarker in different types of cancer." (PMID 35037067, 2022).